SLFN11 (schlafen family member 11)
Diseases named in the same sentence as SLFN11 in open-access papers (continued):
Sharing a sentence is not in itself a finding about the gene and the disease.
tumor (continued). "In our study, SLFN11 expression was present in both UV AS cell lines and in 80% of UV AS tumor samples." (PMID 34085099, 2021). "We propose that the coordinated regulation of SLFN11 across tumor cells and the activated adaptive immune system highlights the potential of this factor as a biomarker for both tumor activity and immune transactivation to platinum-based therapy." (PMID 34549724, 2021). "Of note, SLFN11 was identified as a sensitizer of tumor cells to T cell– and IFN-γ–mediated cytotoxicity." (PMID 34549724, 2021). "We developed a clinically applicable IHC assay to spatially assess SLFN11 expression patterns and prevalence across multiple tumour types and elucidated the role of SLFN11 as a potential biomarker of PARP inhibitor drug sensitivity." (PMID 34663950, 2021). "IHC analysis identified a subset of tumours with sub-clonal SLFN11 expression, where spatially distinct high and low SLFN11 expressing subclones were identified within the same patient sample." (PMID 34663950, 2021). "In total, 15% of SCLC tumours presented with SLFN11 sub-clonality (n = 19/124), and median positivity was generally high at 80%." (PMID 34663950, 2021). "Given the highly significant correlation between SLFN11 mRNA expression and SLFN11 protein expression, RNA sequencing of patient tumor cells can be readily applied to determine the levels of SLFN11 expression." (PMID 34572827, 2021). "We further propose that SLFN11 expression in tumor-infiltrating immune cells mirrors the cellular subset distribution in PBMCs." (PMID 34549724, 2021). "Taken together, these results indicate that, in addition to TILs, other cell populations contribute to SLFN11 protein levels in tumor tissues." (PMID 34549724, 2021). "We developed and validated a clinically applicable SLFN11 immunohistochemistry assay and retrospectively correlated SLFN11 tumour levels to patient outcome to the standard of care therapies and olaparib maintenance." (PMID 34663950, 2021). "Taken together, these results established the analytical validity of our IHC approach to SLFN11 measurement in tumor specimens." (PMID 34549724, 2021). "With regards to translating SLFN11 to the clinic, reliable approaches are required to evaluate the SLFN11 status of tumor tissues and circulating tumor cells (CTCs)." (PMID 34572827, 2021). "In this study, SLFN11 protein levels were evaluated in different tumour models and compared to transcript levels in cell lines of the same tissue of origin." (PMID 33339894, 2021). "After our discovery, several studies confirmed the causal role of SLFN11 in the process of cell death upon DDA treatment in cell lines, organoids, and xenografts from different tumor types." (PMID 34549724, 2021). "SLFN11 re-upregulates in the circulating tumor cells upon treatment with platinum-based drugs, implicating SLFN11 upregulation in the CRPC response to platinum therapy." (PMID 34571887, 2021). "Both ATM upregulation and SLFN11 downregulation can activate EMT to stimulate tumor cells’ resistance to CP." (PMID 32503307, 2020). "We show high PARP1 and SLFN11 expression in DSRCT tumor material and antitumor effects following olaparib and TMZ combination treatment in a preclinical DSRCT model." (PMID 32279088, 2020). "On the other hand, tumor cells are sensitized by SLFN11 to multiple DNA-targeting drugs, including platinum derivatives, PARPi, inhibitors of topoisomerases, and DNA synthesis inhibitors." (PMID 33324554, 2020). "On the other hand, Schlafen 11 (SLFN11) is an onco-suppressor factor that enhances sensitivity of cancer cells into anti-tumor agents." (PMID 32503307, 2020). "Our findings demonstrated that INK128 successfully suppresses the mTOR signaling pathway and attenuates tumor growth and the degree of lung metastasis induced by low SLFN11 expression." (PMID 32292519, 2020).
tumor (continued). "Deficiency of SLFN11 due to mutation or epigenetic silencing by inhibitors of HDAC and EZH2 histone methyltransferase leads to tumor progression and resistance to DNA-targeting drugs." (PMID 33324554, 2020). "We also showed INK128 treatment in mice harboring xenograft tumors with high SLFN11 expression led to a greater reduction in tumor size and metastasis compared with those with low SLFN11 expression." (PMID 32292519, 2020). "Specifically, about 77% of the tumor tissues (72 of 94) with low SLFN11 expression showed moderate or strong RPS4X staining and 64% (56 of 88) of those with high SLFN11 expression displayed negative or weak RPS4X staining." (PMID 32292519, 2020). "The tumor volume was 1204.8 ± 616.3 mm3 in SLFN11 unexpressed MGC803 cell xenografts and 544.9 ± 247.6 mm3 in SLFN11 re-expressed MGC803 cell xenografts." (PMID 31762822, 2019). "Other candidate evofosfamide sensitivity genes—MKI67, POR, and SLFN11—did not strongly influence evofosfamide sensitivity in univariate analyses, although a weak significant relationship with MKI67 was observed, while SLFN11 expression was lost in PDX tumours." (PMID 31337055, 2019). "Across all PDX models, there was a 5.2-fold reduction in SLFN11 expression in P2 tumours vs. P0 tumours, with the greatest difference (a 19.8-fold reduction) observed in ACS-HN04." (PMID 31337055, 2019). "Comparison of SLFN11 transcript levels in baseline (pre-treatment) tumor biopsy specimens showed that patients with CR had significantly higher SLFN11 expression than those that did not (p = 0.045)." (PMID 31682620, 2019). "Collectively, our data indicate that SLFN11 can couple IFN-γ exposure of tumor cells to DDR and cellular apoptosis." (PMID 30753225, 2019). "SLFN11 is a putative DNA-RNA helicase that has been shown to sensitize tumor cells toward DNA damage-induced cell death." (PMID 30753225, 2019). "Determining potential interplay between SLFN11 expression, the tumor microenvironment, and sensitization to chemotherapy represents a logical and clinically important next step." (PMID 31682620, 2019). "Future work should reveal the mechanistic basis for the link between IFNGR signaling and DNA damage response, and identify tumor cell types in which SLFN11 contributes to the anti-tumor activity of T cells." (PMID 30753225, 2019). "We further validated these findings in eight clinical datasets, and showed that higher levels of SLFN11 mRNA expression in treatment-naïve primary tumors predict improved OS and tumor response to chemotherapies." (PMID 31682620, 2019). "Tumor SLFN11 mRNA expression is a biomarker of sensitivity to an array of DNA-damaging chemotherapeutics across solid tumor subtypes." (PMID 31682620, 2019). "SLFN11 is a tumor suppressor in human GC, and methylation of SLFN11 is a cisplatin resistant marker in human GC." (PMID 31762822, 2019). "The tumor volumes were significantly smaller in SLFN11 re-expressed MGC803 cells compared to SLFN11 unexpressed MGC803 cells (P < 0.05)." (PMID 31762822, 2019). "Developing assays for assessing SLFN11 status as a predictive marker for tumor response to DNA damaging agents and clarifying the molecular details underlying SLFN11 biology are pressing tasks for the future." (PMID 27708213, 2016). "In the current study, we found significant correlation between SLFN11 high expression and tumor differentiation." (PMID 26525741, 2015). "They demonstrated that this resistance could be overcome by deacetylase inhibitors, which function to derepress SLFN11 expression, thereby sensitizing tumor cells to chemotherapeutic mechanisms." (PMID 41303540, 2025). "At the same time, SLFN11 is deeply involved in the regulation of the tumor immune microenvironment and is positively correlated with the infiltration of multiple immune cells and the expression of immune checkpoint molecules, suggesting its potential immune regulatory function." (PMID 40766331, 2025).
tumor (continued). "Non-invasive detection methods based on liquid biopsy (such as circulating tumor cells) should be developed to monitor the dynamic changes in SLFN11 expression during the treatment in real time, especially the downward trend of SLFN11 expression after chemotherapy or treatment with PARP inhibitors." (PMID 40766331, 2025). "SLFN11 is known to have a multidirectional role in tumorigenesis and to act as a tumor suppressor." (PMID 40649874, 2025). "However, a retrospective study evaluated the expression of SLFN11 in tumor cells using immunohistochemistry, and when >30% of tumor cells were stained, it was considered SLFN11 immunostaining positive." (PMID 40766331, 2025). "Notably, this patient’s SCLC tumor was positive for SLFN11, which is a dominant determinant of tumor response to TOP1-targeted agents from both the IIQ and CPT classes." (PMID 40439882, 2025). "Interrelations between the expression of SLFN11 and the tumor microenvironment are more complex." (PMID 40105034, 2025). "Phosphorylation of SLFN11 at key sites (e.g., S219, T230, S753) inhibits its ribonuclease activity and its ability to bind single-stranded DNA, thereby impairing its capacity to block DNA replication and induce tumor cell apoptosis." (PMID 41303540, 2025). "All but one tumor with a strong SLFN11 immunoreactivity were right‐sided." (PMID 40105034, 2025). "Increased expression of SLFN11 in noncancerous (tumor-infiltrating lymphocytes, TILs) was strongly associated with better overall outcomes." (PMID 38791884, 2024). "RPS4X levels were shown to be inversely correlated with SLFN11 in HCC tumor tissue." (PMID 38791884, 2024). "SLFN11 is recruited directly to the stalled replication fork in response to replication stress induced by DDAs, and its expression levels exhibit a strong positive correlation with tumor sensitivity to DDAs." (PMID 37894765, 2023). "A possible explanation for this discrepancy could be that the tumor burden is higher in people with shorter survival, higher concentrations of SLFN11 are released into the blood, and the measured concentrations in the serum are higher." (PMID 37894765, 2023). "Recent studies have found that SLFN11 expression is decreased in HCC, suggesting that SLFN11 may play a role in inhibiting HBV-induced HCC tumor progression." (PMID 36672482, 2023). "classified the SLFN11 immunohistochemical staining profiles into three groups, 1+ (1%–10%), 2+ (11%–50%), and 3+ (51%–100%), for semiquantitative evaluation of SLFN11 expression across a wide variety of sections of normal and tumor tissues." (PMID 36741698, 2022). "Independent groups proved that SLFN11 expression in tumor cells could be easily assessed by immunohistochemistry." (PMID 35625957, 2022). "Also, to our knowledge, we showed here for the first time, through an in silico effort and by direct measurement, the presence and localization of SLFN11 in tumor and tumor-infiltrating milieu in patients with HGSOC." (PMID 34549724, 2021). "In addition, we demonstrated expression of SLFN11, a biomarker for response to DNA damaging agents, in 74% of UV AS tumor samples." (PMID 34085099, 2021). "Whilst limitations include the use of a largely SLFN11-negative CRC population (80%) and no Stage I patients, these findings show SLFN11 positivity associates with poor prognosis clinical features in certain tumour types." (PMID 34663950, 2021). "Expression of PARP1 and SLFN11 was present in the majority of UV AS tumor samples." (PMID 34085099, 2021). "By implementing analytic pipelines in clinical material, we demonstrate, for the first time to our knowledge, that SLFN11 in both the neoplastic and microenvironmental compartments of tumor specimens modulates the response to platinum-containing regimens in patients with HGSOC." (PMID 34549724, 2021). "Furthermore, in vitro and in vivo experiments showed that SLFN11 likely functions as a tumor suppressor in HCC progression and metastasis by targeting RPS4X via the mTOR signaling pathway." (PMID 32292519, 2020).
tumor (continued). "The results indicated that SLFN11 might hinder tumor cells into S phase of cell cycle or the progression of S phase." (PMID 32292519, 2020). "Therefore, we examined poly(ADP-ribose) polymerase 1 (PARP1) and Schlafen-11 (SLFN11) expression in DSRCT tumor tissue and the combination of PARP inhibitor olaparib with the alkylating agent temozolomide (TMZ) in a preclinical DSRCT model." (PMID 32279088, 2020). "Notably, we identified schlafen 11 (SLFN11), a known modulator of DNA damage toxicity, as a regulator of tumor cell sensitivity to T cell-secreted IFN-γ." (PMID 30753225, 2019). "In 73 cases of tumor diameter < 5cm of patients, SLFN11 was methylated in 20.55% (15 of 73)." (PMID 31762822, 2019). "Given the role of SLFN11 in sensitization of tumor cells toward DDA-mediated toxicity, we also sought to assess whether there is an association between IFN-γ exposure and induction of a DNA damage response." (PMID 30753225, 2019). "The tumor weights were significantly reduced in SLFN11 re-expressed MGC803 cell tumors (P < 0.001)." (PMID 31762822, 2019). "In 128 cases of tumor diameter ≥ 5cm of patients, SLFN11 was methylated in 35.16% (45 of 128)." (PMID 31762822, 2019). "SLFN11 has been implicated as a key determinant of tumor cell sensitivity to DNA damaging agents, but not other types of chemotherapeutics." (PMID 30753225, 2019). "Patients were dichotomized based on median tumor SLFN11 mRNA expression." (PMID 31682620, 2019). "Our data suggest that evofosfamide sensitivity cannot be robustly predicted by hypoxia, MKI67, POR, or SLFN11 expression on their own, but rather is likely to be multifactorial, incorporating tumour hypoxia and other genes that influence the activation and mechanism of action of evofosfamide." (PMID 31337055, 2019). "Since all tumor samples in our studies were collected before chemotherapy we presume that the observed hypermethylation of SLFN11 in the analyzed tumors confers a growth advantage in these cells and it is also a biomarker of primary resistance to the mentioned drugs." (PMID 26625211, 2016). "However, some studies suggest that the expression level of SLFN11 obtained by tissue RNA-seq may be overestimated in certain tumor tissues." (PMID 40766331, 2025). "Therefore, the dynamic detection of SLFN11 in circulating tumor cells shows special potential." (PMID 40766331, 2025). "Additionally, SLFN11 has emerging significance in shaping the tumor immune microenvironment (TME)." (PMID 40766331, 2025). "However, we might speculate that since this subgroup of survivors achieved a considerable response to chemotherapy, leading to a reduced tumor burden, the secretion of SLFN11 consequently decreased." (PMID 38790938, 2024). "Thus, SLFN11 appears to sensitize tumor cells to TAS1553 via promoting apoptosis." (PMID 35681099, 2022). "Basal SLFN11 expression may, thus, be predictive of tumor sensitivity to PARPi." (PMID 35511434, 2022). "Furthermore, SLFN11 may be a tumor suppressor that blocks mTOR signaling in HCC and therefore a potential therapeutic target in HCC patients." (PMID 34571887, 2021). "Finally, we wondered whether, and to what degree, the SLFN11 expression pattern observed in PBMCs is mirrored in tumor-infiltrating leukocytes in the context of different functional orientation." (PMID 34549724, 2021). "However, to date SLFN11 expression has not been linked to IFN-γ-induced toxicity or resistance to tumor-specific T cells." (PMID 30753225, 2019). "However, SLFN11 is not IFN-stimulated in SCLC cell lines suggesting that expression and regulation of SLFN11 by tumor and immune cells may be different." (PMID 28212573, 2017). "Mechanistic studies have shown that SLFN11 stabilizes RBM10 and promotes NUMB exon 9 skipping by inhibiting TRIM21-mediated RBM10 degradation, a process that is critical for regulating anti-tumor immune responses." (PMID 40766331, 2025).
tumor (continued). "Several of the genes that demonstrated a putative role as predictive biomarkers are either well-known tumor suppressors (RASSF1, XAF1, ASC/TMS1, ASPP1, DAB2IP) or DNA damage response regulators (SLFN11)." (PMID 39051186, 2024). "We believe in-dept exploration of the feedback loop observed between tumor cells SLFN11 expression and T-cells IFN-γ expression is required to understand the DNA damage response mechanisms interactions with the anti-tumor immune response." (PMID 38001424, 2023). "IHC analysis indicated a strong expression of SLFN11 in patient L4 TB at progression and in the corresponding CDX tumor." (PMID 35511434, 2022). "Here, we explored the effects of Schlafen family member 11 (SLFN11) in the molecular, cellular, and tumor biology of GBM." (PMID 36382088, 2022). "Genetic disruption of SLFN11 stimulated expression of NFκB target genes, including CDKN1A (p21) and significantly delayed tumor growth and improved survival in a GBM orthotopic patient-derived xenograft (PDX) mouse model." (PMID 36382088, 2022). "Nevertheless, additional investigations are warranted to confirm the correlation between SLFN11 overexpression and NSCLC tumor response to olaparib." (PMID 35511434, 2022). "The results showed that the high SLFN5, SLFN11, SLFN12, SLFN12L, and SLFN13 expression in GC was positively correlated with lymph node metastasis, tumor stage, and tumor grade." (PMID 36090985, 2022). "Accordingly, following IFN-γ exposure, SLFN11 has been shown to couple IFN-γ receptor signaling to the induction of DNA damage and cell death in tumor cells in a context-dependent fashion." (PMID 34549724, 2021). "SLFN11 expression is negatively correlated with high serum alpha-fetoprotein levels (a marker widely used to detect HCC), tumor size, microvascular invasion, and advanced stage." (PMID 34571887, 2021). "To further evaluate the effects of SLFN11 and INK128 on tumor growth and metastasis, we established orthotopic xenograft mouse models of HCC (6 mice per group)." (PMID 32292519, 2020). "Surprisingly, we identified SLFN11, an IFN-inducible gene previously shown to influence tumor cell sensitivity to DNA damaging agents (DDA), as a modulator of HAP1 sensitivity to T cell attack." (PMID 30753225, 2019). "The xenograft tumor weight was 0.709 ± 0.071 g in SLFN11 unexpressed MGC803 cell tumors and 0.352 ± 0.099 g in SLFN11 re-expressed MGC803 cell tumors." (PMID 31762822, 2019). "Here we demonstrate that SLFN11 expression can regulate IFN-γ-mediated toxicity and, as a consequence, sensitivity of tumor cells to T cell attack." (PMID 30753225, 2019). "We then correlated SLFN11 expression with clinicopathological features of CRC, including primary tumor location, tumor differentiation, preoperative Cancinoembryonic Antigen(CEA) level, TNM staging, KRAS exon 2 status, age and sex." (PMID 26525741, 2015). "Given the limited availability of tumor biopsies in advanced SCLC, SLFN11 expression in circulating tumor cells (CTCs) is a noninvasive biomarker for monitoring treatment response and resistance, facilitating personalized therapeutic strategies." (PMID 41194225, 2025). "In tumor-infiltrating lymphocytes (TILs), the expression level of SLFN11 in non-tumor cells is positively correlated with the number of TILs." (PMID 40766331, 2025). "In addition to SLFN11-related pathways, the DNA repair capabilities are often enhanced in SCLC tumors, enabling tumor cells to survive treatment with chemotherapy, which works by damaging DNA." (PMID 41194225, 2025). "After DNA damage induction, SLFN11 selectively inhibits the translation of key DDR repair genes (such as ATR and ATM) by mediating tRNA downregulation, thereby impairing the repair capacity of tumor cells." (PMID 40766331, 2025). "A further mechanism analysis revealed that SLFN11 may inhibit the mTOR signaling pathway through RPS4X, while the mTOR pathway inhibitor INK128 could achieve a similar tumor suppression effect." (PMID 36672482, 2023).